CAT (catalase)
Diseases named in the same sentence as CAT in open-access papers (continued):
Sharing a sentence is not in itself a finding about the gene and the disease.
schizophrenia (55 papers, 2011 to 2025). A major psychotic disorder characterized by abnormalities in the perception or expression of reality. "Based on prior literature, this study aimed to investigate MPO and CAT levels and their diagnostic value in schizophrenia patients." (PMID 41300145, 2025). "Our results that the reduced of MDA level and the increased CAT activity in plasma in male patients with chronic schizophrenia suggest that redox imbalance may be associated with the pathophysiology of schizophrenia, and it can induce impaired cognition and psychiatric symptoms." (PMID 35757215, 2022). "RFE (1 mg/kg), both alone and in combination with CLZ, significantly enhanced prefrontal cortical CAT levels, highlighting its potential to counteract oxidative stress in schizophrenia." (PMID 40368975, 2025). "CAT activity was significantly higher in schizophrenia patients than healthy controls, medians were 22.06 ng/mL and 6.58 ng/mL respectively, p < 0.001." (PMID 41300145, 2025). "Essential findings of our study are as following: increased MDA, MPO and CAT levels in overall schizophrenia patients and subgroups of patients." (PMID 41300145, 2025). "There is substantial evidence indicating that patients diagnosed with schizophrenia exhibit significantly reduced activities of key antioxidant enzymes, including glutathione peroxidase, superoxide dismutase, and catalase." (PMID 41011215, 2025). "catalase activity in patients with schizophrenia is relatively weak, contributing to elevated oxidative stress levels and thus participating in disease progression." (PMID 40103865, 2025). "One of the studies conducted by Dariusz Juchnowicz revealed changes of catalase and glutathione peroxidase, which can be determining factors of schizophrenia." (PMID 40092138, 2025). "We aimed to investigate serum myeloperoxidase (MPO), catalase (CAT), and malondialdehyde (MDA) levels and their diagnostic value in schizophrenia." (PMID 41300145, 2025). "In this study, we demonstrated that serum MDA, MPO, and CAT levels were significantly elevated in schizophrenia patients compared with healthy controls." (PMID 41300145, 2025). "In contrast to MPO, CAT has been widely investigated in schizophrenia, with decreased, unaltered, and increased levels reported." (PMID 41300145, 2025). "As with SOD, research on CAT levels in patients with schizophrenia has had varied results, reflecting the complexity of oxidative stress and antioxidant defense mechanisms in this disorder." (PMID 39734678, 2024). "A study of patients with schizophrenia reported significantly lower CAT and GSH-Px levels compared to healthy controls." (PMID 39473913, 2024). "Earlier, benzoate was also able to increase plasma CAT in treatment‐resistant schizophrenia patients; importantly, the CAT increment was positively related with clinical improvement." (PMID 36335573, 2023). "In previous studies carried out, SOD and CAT activities in schizophrenia patients were found to be higher in those treated than in those untreated." (PMID 36831126, 2023). "According to the results of the experiment, the catalase activity of the IgGs from the patients in the acute phase of schizophrenia is three times lower as compared to the healthy individuals (p = 0.02)." (PMID 37185730, 2023). "IgG catalase activity has been found to be significantly higher in patients with schizophrenia and multiple sclerosis than in apparently healthy donors." (PMID 37373231, 2023). "Plasma MDA levels and MnSOD and GSH-Px activities were significantly lower in schizophrenia patients than in healthy controls (P < 0.001), while plasma CAT activity was higher than in healthy controls (P < 0.005)." (PMID 35757215, 2022). "The catalase activity was lower in schizophrenia patients at the beginning of the disease (p < 0.01), while the GPx activity was lower in those who were suffering from it for over a year (p < 0.01)." (PMID 36295651, 2022).
schizophrenia (continued). "Materials and Methods: Catalase and GPx activities were determined in the erythrocytes of 68 inpatients with schizophrenia and 59 age- and gender-matched healthy controls." (PMID 36295651, 2022). "IgGs of patients with schizophrenia (36.4%) and from healthy donors (33.3%) possess catalase activity." (PMID 35409256, 2022). "Studies have shown in schizophrenia an increase in oxidative stress, in conjunction with a decrease in antioxidant defense enzymes (e.g., superoxide dismutase (SOD), catalase, and glutathione peroxidase) in schizophrenia." (PMID 32620164, 2020). "Another study has demonstrated that the altered activities of SOD, CAT, and GPx damage lipids and proteins in a schizophrenia rat model." (PMID 32793005, 2020). "In human brains, CAT was upregulated in schizophrenia samples compared to the controls (Fig EV5A), and the expression level of this gene was positively correlated with that of MPST and CBS in both the schizophrenia and control samples (Fig EV5B and C)." (PMID 31657521, 2019). "In this case, the specific processes occurring in schizophrenia patients can lead to an increased production of the pool of auto-Abs including abzymes with high catalase activity." (PMID 28945759, 2017). "In this report, we have shown the first evidence of catalase activity of polyclonal IgGs isolated from the sera patients with schizophrenia and healthy donors." (PMID 28945759, 2017). "Antioxidant enzymes such as SOD, GpX and CAT are most commonly measured for quantifying the antioxidative defense in schizophrenia, along with vitamin E and C levels." (PMID 22131939, 2011). "Catalase activity has been investigated widely in schizophrenia patients." (PMID 41300145, 2025). "Another study denoted unchanged CAT levels in drug free schizophrenia patients." (PMID 41300145, 2025). "While evaluating our data with existing knowledge, the increased CAT activity may be due to antipsychotic effect or the chronicity of schizophrenia." (PMID 41300145, 2025). "Our SOD assay revealed that the activity of the serum IgG from the patients with schizophrenia is significantly higher as compared to healthy people, while the catalase activity in the same pool of immunoglobulins G is significantly lower relative to healthy individuals." (PMID 37185730, 2023). "In 2017, all the necessary experiments for the first time were performed to prove the assignment of catalase activity directly to antibodies, and showed, using IgGs of healthy donors and patients with schizophrenia, that human polyclonal IgGs possess catalase activity." (PMID 35409256, 2022). "IgG in schizophrenia patients has catalase activity that could play a role in protecting organisms from oxidative stress." (PMID 36143234, 2022). "In addition, immunoglobulins from healthy people, patients with schizophrenia or multiple sclerosis, and mammals have been demonstrated to exhibit peroxidase and catalase activity." (PMID 36143234, 2022). "In addition, our recent studies conducted together with the Institute of Chemical Biology and Fundamental Medicine (Novosibirsk, Russia) have reported catalase (CAT) activity in IgGs of patients with schizophrenia." (PMID 32089782, 2020). "Moreover, an up-to-date collective report emphasizes the association between schizophrenia and oxidative stress markers, which includes a decline in antioxidant levels such as GSH and catalase, coupled with an elevation in markers of lipid peroxidation (LPO) in the peripheral system." (PMID 38256307, 2023). "However, our previously published results showed significantly higher erythrocyte SOD activity in the same group of patients with schizophrenia, which could result in increased hydrogen peroxide production, which provides more substrates for catalase and GPx." (PMID 36295651, 2022).
schizophrenia (continued). "The relative catalase activity of IgGs from the sera of individual schizophrenia patients (and healthy donors) significantly varied from patient to patient, but the activity of IgGs from healthy donors is on average 15.8-fold lower than that for schizophrenia patients." (PMID 28945759, 2017). "Catalase activity in schizophrenia has been reported as increased, unchanged, or reduced by different investigators, although it is likely that peripheral levels poorly approximate brain levels of catalase especially since catalase activity can be dramatically altered by antipsychotic medications." (PMID 24868318, 2014). "Researchers have found that serum superoxide dismutase (SOD) is significantly lower and catalase (CAT) and malondialdehyde (MDA) levels are significantly higher in patients with schizophrenia compared to the normal population." (PMID 40060748, 2025). "The present study showed that activities of Mn-SOD, CuZn-SOD, T-SOD, GSH-Px, and levels of H2O2, MDA were lower, whereas CAT activity and MMP-9 levels were higher in patients with schizophrenia than in healthy controls." (PMID 38172869, 2024). "Levels of the major antioxidant enzymes, superoxide dismutase (SOD), catalase (CAT), and glutathione peroxidase (GSH-Px), were decreased in patients with schizophrenia compared with controls." (PMID 39234617, 2024). "Our results demonstrated that levels of antioxidant enzymes, SOD, GSH-Px, H2O2, and MDA were significantly decreased, whereas CAT and MMP-9 levels were increased in patients with schizophrenia, when compared with healthy controls (all P < 0.05)." (PMID 38172869, 2024). "Individuals undergoing treatment for schizophrenia exhibit reduced levels of glutathione (GSH), superoxide dismutase (SOD), and catalase (CAT)." (PMID 38721610, 2024). "Patients with schizophrenia have imbalances in antioxidant enzymes, such as glutathione peroxidase (GPx), superoxide dismutase (SOD), catalase (CAT), and reduced levels of antioxidants (vitamin E, vitamin C)." (PMID 39734678, 2024). "Numerous earlier studies including clinical and nonclinical have demonstrated the contribution of OS imbalance, such as CAT, superoxide dismutase (SOD), GSH-Px, and malondialdehyde (MDA), to the pathophysiological mechanisms of schizophrenia." (PMID 38172869, 2024). "Disturbances in the balance between the antioxidant enzymes CAT, SOD, and GSH-Px and H2O2 and MDA lead to OS, and antioxidant therapy has been shown to be effective in improving symptoms of schizophrenia." (PMID 38172869, 2024). "Animal models of schizophrenia indirectly demonstrated the relationship between increased activities of SOD and CAT and behavioral deficits in rats." (PMID 38172869, 2024). "Over the past few years, abzymes with nuclease, proteolytic, catalase, and superoxide dismutase (SOD) activities have been found in the blood serum of patients with schizophrenia." (PMID 37185730, 2023). "Compared to controls, reduced glutathione (GSHr), catalase (CAT), and superoxide dismutase (SOD) levels were found to be significantly lower in schizophrenia patients." (PMID 36831126, 2023). "For example, in a rat model of schizophrenia, inhibitors of TDO, IDO and KMO were able to prevent lipid peroxidation, decrease protein carbonyl levels, and increase SOD levels and catalase activity." (PMID 35682980, 2022). "When all schizophrenia patients (G1 + G2) were compared to the control group, SOD levels were found to be lower among schizophrenia patients (p < 0.0001), while MDA and CAT levels were higher (p < 0.0001 and p = 0.0191, respectively)." (PMID 34982515, 2021). "In conclusion, increased MDA and CAT levels and decreased SOD levels indicate that schizophrenia patients are exposed to oxidative stress." (PMID 34982515, 2021). "It was shown that thioridazine and chlorpromazine evoked oxidative stress in serum of schizophrenia patients in whom the increase of SOD and CAT activity was observed." (PMID 26105001, 2015).
schizophrenia (continued). "The largest body of evidence of lipid peroxidation in schizophrenia is from indirect markers such as activity of SOD, catalase, and glutathione peroxidase." (PMID 24868318, 2014). "Previously, it was found that close relatives of patients with schizophrenia had lower levels of SOD and CAT (similar to patients) and higher levels of cGPx than healthy control subjects." (PMID 23158023, 2012). "Although in patients with schizophrenia compared to controls, significant changes were observed in nitric oxide (NO) levels, but not in catalase (CAT) levels." (PMID 40092138, 2025). "In brief, we found MPO, CAT and MDA were increased in schizophrenia patients." (PMID 41300145, 2025). "When comparing the results related to schizophrenia patients and their healthy twin pairs, significantly lower activities of SOD, GPx, and catalase were found in patients, whereas the GPx activity was significantly higher in healthy twin pairs than that in the control group." (PMID 36295651, 2022). "In schizophrenia, there is either reduction in primary antioxidants levels including superoxide dismutase (SOD), CAT and glutathione peroxidase (GPx), or a decrease in the secondary antioxidants such as glutathione, vitamins B6 (pyridoxine), B9 (folate), B12 (cobalamin), C, D, and E." (PMID 33995058, 2021). "Then, amounting studies have subsequently documented increased OxS and oxidative injury as well as an impaired antioxidant defense system in patients with schizophrenia, such as superoxide dismutase (SOD), glutathione peroxidase (GSH-Px), catalase (CAT), and malondialdehyde (MDA)." (PMID 34526062, 2021). "Lower SOD levels and higher MDA and CAT levels indicate oxidative damage in schizophrenia patients, regardless of their response to pharmacological treatment." (PMID 34982515, 2021). "Using this methodology, a recent meta-analysis found that total antioxidant status, as well as red blood cell (RBC) catalase and plasma nitrite appeared to be state markers of schizophrenia, while RBC superoxide dismutase appeared to be a trait marker for schizophrenia." (PMID 28304340, 2017). "We have applied several previously developed strict criteria proving that the catalase activity of IgGs of the sera schizophrenia patients and healthy donors belongs to the Abs and is not due to co-purifying enzymes." (PMID 28945759, 2017). "A recent extensive review on studies on the relationship between schizophrenia and oxidative stress found that peripheral markers of GSH were consistently decreased, but found equivocal results for other antioxidants such as superoxide dismutase and catalase." (PMID 28304340, 2017). "Enzymes such as catalase, GPx, and SOD, along with vitamins E and C, are typically measured to quantify the antioxidant defense system in schizophrenia patients; such antioxidants may also, therefore, have a therapeutic effect on schizophrenia." (PMID 33081261, 2020). "In our study, many RB (CAT, GR, SOD-1, FRAP, AGEs, DITYR, NFK, TYR) were not related to schizophrenia." (PMID 34575267, 2021).
type 2 diabetes (55 papers, 2008 to 2025). "Genetic abnormalities in catalase levels and function have been shown to be associated with the onset of type II diabetes, suggesting an impact of the activity of catalase upon insulin signalling." (PMID 24211250, 2014). "Mutations in CAT, elevating hydrogen peroxide, may increase type 2 diabetes risk due to peroxide-induced beta cell damage." (PMID 39080045, 2024). "Catalase is associated with various human diseases, including osteoarthritis, cancer, psoriasis and other skin disorders, ischemia-reperfusion injury, neurodegenerative disorders, and type 2 diabetes." (PMID 27597806, 2016). "Conversely, catalase exhibited a decreased AOR for type 2 diabetes (AOR = 0.33; 95% CI = 0.22–0.49, p‐value < 0.001)." (PMID 38274131, 2024). "In another study, a GL polysaccharide showed a potent antioxidant effect via improving SOD, GSH-Px, and CAT activities in the liver of type 2 diabetic rats." (PMID 37138906, 2023). "Reducing oxidative stress and maintaining SOD, catalase, and MDA activities may be crucial components of type 2 diabetes care to reduce the risk of diabetic complications." (PMID 38274131, 2024). "Generally, blood catalase activity in type 2 diabetes is highly reduced." (PMID 39065816, 2024). "Additionally, the associations between the risk of type 2 diabetes, MDA, SOD, and catalase levels were consistent with those reported in a previous study." (PMID 38274131, 2024). "Our findings agree with others showing increased ROS levels and anti-oxidant imbalance in the placenta involving increased catalase expression in various rodent models where type-1 and type-2 diabetes were induced via genetic, surgical and pharmacological methods." (PMID 38526599, 2024). "This study suggests that 400 μg/mL of K. pinnata may reduce oxidative damage by increasing catalase activity in human skeletal muscle cells compared to other treatment groups and may be beneficial in reducing oxidative stress in type II diabetes." (PMID 37047182, 2023). "One immediate hypothesis can be generated is that human gut microbiota contribute to type 2 diabetes by producing butyric acid in digestion of dietary fiber, which can then target catalase gene/protein in human body." (PMID 32561832, 2020). "In type 2 diabetic patients, the downregulation of catalase synthesis may result in decreased blood catalase activity, thereby increasing HP production." (PMID 25243114, 2014). "In type 2 diabetic rats, elevated MDA levels and decreased TAC, SOD, and CAT occurred, and NSSP treatment (35, 70, and 140 mg/kg for 4 weeks, orally) improved oxidant/anti-oxidant balance." (PMID 38911247, 2024). "Patients with type 2 diabetes have been shown to have lower SOD activity, a sign of higher oxidative stress, and catalase overexpression lowers the expression of angiotensinogen and apoptosis in diabetic mice." (PMID 38274131, 2024). "Numerous previous studies have confirmed the ability of ULP to alleviate the symptoms of type 2 diabetes by reducing blood glucose levels through enhanced insulin sensitivity, as well as boosting superoxide dismutase (SOD) and catalase (CAT) activity." (PMID 39596859, 2024). "Among three types of liposomes, HDCA:ME-(1:1)-Lips significantly reduced the fasting blood glucose levels, improved glucose tolerance, and regulated biochemical indices (TC, TG, INS, GLP-1, SOD, CAT, and MDA) in type 2 diabetic mice." (PMID 36985444, 2023). "Similar to this study, the administration of polysaccharides of Lonicera japonica showed protective effects on hepatic antioxidant deficits by increasing the expression levels of CAT, SOD, and GSH in type 2 diabetic SD rats." (PMID 37107342, 2023). "AST can increase the levels of antioxidants catalase (CAT), superoxide dismutase (SOD), and glutathione peroxidase (GPx) in the hippocampus of type 2 diabetic rats, therefore, increasing the antioxidant capacity of the hippocampus." (PMID 35646393, 2022).